RNY4P20 (RNY4 pseudogene 20)
Gene: Miscellaneous RNA gene on chromosome 6 (151,298,841 to 151,298,933, reverse strand). Ensembl gene ENSG00000252487.
Homologues: Orthologues: chimpanzee Y_RNA (98% identical), macaque Y_RNA (95% identical), guinea pig Y_RNA (87% identical). Paralogues in human: RNY4 (90% identical), RNY4P6 (88% identical), Y_RNA (87% identical), RNY4P13 (86% identical), RNY4P17 (86% identical), RNY4P14 (85% identical), RNY4P7 (85% identical), Y_RNA (85% identical), RNY4P10 (84% identical), RNY4P19 (84% identical), RNY4P3 (84% identical), Y_RNA (84% identical), and 90 more.